HIF1A (hypoxia inducible factor 1 subunit alpha)
Diseases named in the same sentence as HIF1A in open-access papers (continued):
Sharing a sentence is not in itself a finding about the gene and the disease.
tumor (continued). "In response, cells from the primary tumor can produce hypoxia-inducible factors (HIFs), in particular HIF-1α which reprograms tumor cells and signaling pathways and regulates oncogenesis, angiogenesis, and metastasis." (PMID 36212456, 2022). "Consistently, our study showed that M protein of SARS-CoV-2 activated the NFκB pathway, which is responsible for the upregulation of EMT and tumor progression-related genes, such as Zeb1/2, Snail, Twist and HIF-1α, in MDA-MB-231 cells." (PMID 35747796, 2022). "Consistent with an immune suppressive role for a tumor hypoxic response, targeting HIF-1α on tumor cells increased CTL infiltration and improved combination immunotherapy outcomes in a preclinical mouse melanoma model." (PMID 35039633, 2022). "Intra-tumor hypoxia mechanism is based on the upstream activation of mTor/HIF-1α by RAS/MAPK and Pi3K/AKT pathways." (PMID 35326631, 2022). "In a hypoxic environment, ALDOA can mediate EMT in tumour cells by regulating hypoxia inducible factor-1α (HIF-1α), which enhances tumour cell migration." (PMID 36494481, 2022). "For example, hypoxia, which is one of the major hallmarks distinguishing solid tumors from normal tissues, was reportedly responsible for inducing PD-L1 in tumor and myeloid cells via HIF-1α." (PMID 35239514, 2022). "Next, the tumor tissues were sectioned and stained, and similarly, the results confirmed high expression of HIF-1α and glycolysis-related genes like LDHA, HK2, PKM2 in the control group and low expression in the shFAM83A-AS1 LUAD." (PMID 35002507, 2022). "Immunoreactivity of HIF-1α significantly differed by lymphovascular invasion (p = 0.009), peri-neural invasion (p = 0.002), tumor regression score (p < 0.001), pathologic complete response (p = 0.01), and HbA1c level (p = 0.046)." (PMID 36011045, 2022). "It is imperative to mention that HIF1α stabilization leads to the glioma stem cell (GSC) population expansion within the tumor mass through Phosphatidyl Inositol 3-Kinase (PI3K)/Protein kinase B (PKB or AKT) pathway." (PMID 35870078, 2022). "Tumor cell factors derived from HCC samples induced CA12 upregulation in tumor-infiltrating TAMs via the HIF1α pathway." (PMID 35362482, 2022). "Under hypoxic conditions, silencing of FOXO1 increased HIF-1α expression in GC cells and xenograft models accompanied by increased angiogenesis and tumor growth." (PMID 35681691, 2022). "To validate the observed increase in LDHA expression in GP5 tumours, we analysed the nuclear expression of HIF-1α using IHC." (PMID 35075123, 2022). "Tumor hypoxia in multiple myeloma activates HIF1α, which promotes cell survival, motility, invasiveness, drug resistance, and neoangiogenesis and is associated with a more aggressive tumor." (PMID 36232447, 2022). "In response to a reduced oxygen level, activation of HIF-1α regulates the transcription of a set of hypoxia-response proteins, including those involved in processes such as invasion and tumor cell migration, which are related to tumor progression." (PMID 35408505, 2022). "Recent studies have found that FHL3 can decrease the expression and promoter activity of vascular endothelial growth factor (VEGF) in tumor angiogenesis by inhibiting both HIF-1α and HIF-1β." (PMID 35686099, 2022). "Under hypoxic conditions, tumour cells activate the evolutionarily conserved hypoxic response through stabilizing HIF-1α that forms a HIF-1 heterodimer through interacting with HIF-1β." (PMID 35501821, 2022). "High-expression of HIF-1α impairs CD8+ TILs, as evidenced by the delay of tumor progression in mice treated with HIF-1α-knockdown CD8+ T cells." (PMID 36618408, 2022). "HIF-1α expression was correlated positively with tumor grade (p = 0.015) and Ki-67 expression (p = 0.001) and negativity with progesterone receptors (PR) (p = 0.04) and luminal A phenotype expression (p = 0.005)." (PMID 36358811, 2022).
tumor (continued). "Due to the gap between in vitro and in vivo experiments, to further confirm the effect of HIF-1α on tumor cell proliferation in vivo, we injected HIF-1α overexpressed C33a cells and HIF-1α-knockout SiHa cells into nude mice." (PMID 35664561, 2022). "As a result, the antioxidants (NADPH and glutathione) produced by glycolysis can efficiently absorb the ROS produced by IR in cancer cells, resulting in the stabilization of HIF-1α and its radioprotective effect in tumor cells under normoxia." (PMID 35328212, 2022). "Many components of S. miltiorrhiza have been demonstrated to suppress tumor cell invasion and metastasis via regulating HIF-1α- and VEGF- mediated signaling pathways." (PMID 36172186, 2022). "In the case of MDSCs, HIF-1α regulates the differentiation and function of MDSCs in the TME and, in fact, facilitates the differentiation of M-MDCs into tumor-associated macrophages." (PMID 36613878, 2022). "Tumor-cell-derived lactic acid facilitate M2-polarization of TAMs through improved arginase and HIF-1α stabilization." (PMID 36038935, 2022). "HIF-1α also has a prominent role in angiogenesis by affecting cellular metabolism, tumor invasion, vascular endothelial growth factor (VEGF), cell survival, and metastasis." (PMID 36224606, 2022). "Hypoxic conditions of the tumor microenvironment also regulate GLUT gene expression via modulation of HIF1α and its downstream signaling events." (PMID 36386187, 2022). "Despite the fact that it inhibits HIF-1α, microtubules, and tumor angiogenesis and has a role in antiproliferation and antiangiogenesis, the role and mechanism of 2-ME2 in CML are still unclear." (PMID 35528614, 2022). "HIF-1α plays multiple roles in tumor progression and metastasis and the development of inhibitors that target this pathway is of great interest." (PMID 35465332, 2022). "XBP1 aggravates hypoxia-inducible factor 1α (HIF1α) and activates its downstream pathways, leading to tumor angiogenesis and increased energy supply to support tumor progression and recurrence." (PMID 35884393, 2022). "Tumor volume and proliferation of HIF1A knock-down tumors decreased significantly upon 5-FU treatment in both WT and 5-FU-R groups." (PMID 34998404, 2022). "On the contrary, undertreated tumor portions after incomplete treatment have characteristic viable tumor features with the overexpression of HIF-1α and other markers of tumor progression." (PMID 35619923, 2022). "In the tumor microenvironment (TME) the genes induced by HIF-1α and HIF-2α enhance tumor growth and survival, by increasing angiogenesis, cell survival, cell proliferation, metastasis, pH regulation, glycolysis and maintenance of cancer stem cells." (PMID 35392965, 2022). "ERRα cooperates with HIF-1α to regulate angiogenesis and glycolysis, thus promoting the growth of tumor cells under hypoxia, while stable HIF-1α further increases the expression of ERRα at the transcriptional level." (PMID 35800058, 2022). "In healthy cells, HIF-1α is rapidly degraded, while in tumor cells, intracellular ascorbate and glutamate levels can affect these pathways resulting in HIF-1α accumulation." (PMID 33417986, 2021). "Intriguingly, HIF-1α immunoreactivity was predominantly localized to the cytoplasm of tumor cells, and exhibited a punctate staining pattern with occasional speckles noted in nuclei." (PMID 33889304, 2021). "Under hypoxic conditions, PrPC induces tumor progression in CRC by targeting the heat shock protein 70 member 1-like (HSPA1L)/HIF-1α/GP78 signal axis." (PMID 33946823, 2021). "Lactic acid produced by tumor cells acts as a signaler through HIF-1α and induces VEGF expression and particularly Arg1 production and M2 polarization." (PMID 34356862, 2021). "Although HIF-1α is thought to be the major regulator of energy metabolism reprogramming in hypoxic tumor cells, microRNAs and circular RNAs can also participate in this regulation." (PMID 33806538, 2021).
tumor (continued). "Considering the diversity of tumor vascular perfusion pathways, drugs targeting HIF-1α, angiogenesis, or VM represent an attractive therapeutic target in CM." (PMID 34476217, 2021). "Genetic screen data indicates that, in normoxia, HIF1A displays strong cell-autonomous tumor suppressive effects through a gene module mediating mTOR inhibition." (PMID 33654095, 2021). "Apart from HIF-1α, redox in the tumor microenvironment can affect intracellular signaling by regulating several membrane receptors, including integrins and TGF-βreceptors, leading to cancer dormancy." (PMID 34685686, 2021). "The in vivo data confirmed that Huaier obviously decreased tumour volume and tumour growth, reduced the glycolysis, glucose transport and HIF‐1α expression in the tumour‐bearing tissues." (PMID 33377619, 2021). "Many studies have reported poor survival and prognoses in HGG patients with high levels of HIF-1α, PDKs, and tumor lactate concentrations, and inhibition of HIF-1α in hypoxia increases the radiosensitivity of HGGs." (PMID 34298883, 2021). "HIF-1α plays a regulatory role of hypoxia on tumor cell genes and promotes the survival of tumor cells in hypoxic microenvironment." (PMID 34660700, 2021). "Treatment of the tumor cells with MJ resulted in a significant decline in the expression of HIF-1α and HK 2 compared to control." (PMID 33716751, 2021). "HIF1α up-regulates a number of genes that support tumor cells to adopt to the hypoxic microenvironment." (PMID 34221996, 2021). "Hypoxia, via the induction of an α subunit of hypoxia-inducible factor-1 (HIF1A), triggers a sequence of events promoting the evolution of aggressive clones from heterogeneous tumor cells." (PMID 33810575, 2021). "In nude mice in vivo, HIF1A overexpression reversed the inhibitory effects of OR7E156P knockdown on tumor growth." (PMID 34422645, 2021). "Third, TAMs contribute to T cell immunosuppression, promoting tumor growth and metastasis through the expression of hypoxia-inducible factor 1-alpha (HIF-1α)." (PMID 33922362, 2021). "As a transcriptional factor by hypoxia, HIF1α actively participates in the regulation of a complex transcription regulatory network central to tumor growth, enabling CC progression." (PMID 34752201, 2021). "HIF-1α is highly expressed in hypoxic tumor cores and is responsible for promoting the expression of pro-angiogenic proteins which are essential for tumor neovascularization and survival." (PMID 34440874, 2021). "VHH212 was stably expressed in tumor cells with low cytotoxicity, high affinity, specific subcellular localization, and neutralization of HIF-1α in the cytoplasm or nucleus." (PMID 33830713, 2021). "HIF‐1α (hypoxia‐inducible factor 1 subunit α) can improve the survival ability and characteristics of various types of tumour cells or organs in a hypoxic environment." (PMID 34755451, 2021). "UALCAN analysis revealed that HIF1A was highly expressed in primary SC tumor tissues relative to normal tissues." (PMID 34621671, 2021). "It has been previously shown that the expression of miR-210, a demonstrated master hypoxamir, is regulated by HIF-1α in a variety of tumor types." (PMID 34465330, 2021). "When the cancer progress, oxygen within the necrotic tumor-core becomes depleted, resulting in hypoxia and a higher intracellular level of hypoxia inducible factor (HIF-1α and HIF2α) through degradation of VHL." (PMID 34131104, 2021). "In contrast to many tumor types, HIF1α and HIF2α have opposite roles in ccRCC biology, where HIF1α acts as a tumor suppressor and HIF2α acts as an oncogene." (PMID 34098990, 2021). "The role of HIF1α in promoting proliferating and immunosuppressive tumor cells and MDSCs is clear, while in modulating T cells, it is still controversial and strictly dependent on different microenvironment scenarios." (PMID 33923299, 2021).
tumor (continued). "It is likely that HIF1α plays both oncogenic roles (less common) and tumor suppressor roles (more common), which depends on the signal network context and/or cell type." (PMID 34384473, 2021). "In animal models, inhibition of HIF-1α was shown to significantly reduce tumor growth, vascularization, and metastasis." (PMID 33921487, 2021). "These NPM1/HIF‐1α co‐upregulated genes are enriched in three different cancer types, and their expression correlates with hypoxic tumor status and worse patient prognosis." (PMID 34388291, 2021). "They made clear that miR-19a-3p is in direct contact with HIF-1α, and simvastatin regulate growth of tumor cells through this mechanism possibility." (PMID 34895042, 2021). "The combination of radiation and deguelin significantly decreased tumor growth and reduced HIF-1α expression in the analyzed xenografts." (PMID 33401572, 2021). "Overexpression of HIF-1α in tumor cells is closely connected with increased resistance to radio- and chemotherapies, increased risk of metastasis, more aggressive phenotype, and strengthened immune suppression." (PMID 33029691, 2021). "Recent experiments using tumor cell lines also support that hypoxia-induced HIF-1α can increase PD-L1 expression on tumor cells, via direct interaction with a hypoxia-response element in the PD-L1 proximal promoter to activate transcription." (PMID 34381712, 2021). "The generation of ROS levels in cancer cells prompted by 27-hydroxycholesterol (27HC) and deferoxamine (DFO) activates STAT-3/VEGF and ERK1/2/HIF1α signaling pathways, promoting tumor angiogenesis and metastasis." (PMID 33916438, 2021). "In our study, we analyzed the relationship between HIF-1α level and clinical stage, as well as correlation between HIF-1α level and tumor diameter of biopsy site." (PMID 33441708, 2021). "HIF1α also supports metabolic adaptation to the tumor environment by upregulating key glycolysis genes to support cell proliferation and survival." (PMID 34396954, 2021). "To probe the pathophysiological significance, we investigated the relative levels of HACE1 and HIF1α protein in WT cases compared with patient-matched normal kidney adjacent to tumor tissues." (PMID 33603169, 2021). "A wealth of evidence proves that high expression levels of HIF-1α in solid tumors and during tumor growth are significantly limited after knocking out HIF-1α, which indicates that HIF-1α plays a vital role in cancer development." (PMID 34365889, 2021). "Information regarding the role of HIF2-α in hypoxia-related angiogenesis in tumor microenvironment is more controversial than for HIF-1α." (PMID 33472628, 2021). "Together these data indicate that ZWINT is transcriptionally upregulated by HIF1α in the hypoxic tumor micro-environment." (PMID 34900978, 2021). "It inhibits the expression of vascular endothelial growth factor (VEGF) via alpha-1 hypoxia inducing factor degradation (HIF-1α) and the growth of human cervical carcinoma HeLa cells and neuroblastoma cell lines, a paediatric tumour." (PMID 34916943, 2021). "The correlation between HIF1A expression and exhausted T cell and iTreg became stronger after tumor recurrence." (PMID 34305618, 2021). "The expression of miR101 in exosomes was suppressed by hypoxic stress, since depletion of HIF1α in tumor cells recovered the miR101 expression in both tumor cells and exosomes." (PMID 34362882, 2021). "Despite the fact that bevacizumab (0.1 mg/kg/mouse) effectively inhibited tumor growth, remarkable overexpression of HIF1α, VEGF, VEGFR1, and CA IX was observed in the treated tumors." (PMID 34948200, 2021). "Here, we demonstrated a new regulatory axis in the hypoxic tumor microenvironment involving elevated NRP1 expression induced by HIF-1α." (PMID 33850110, 2021). "Previous work has reported that CA9 is transcriptionally activated by HIF1α in a broad spectrum of tumor cells." (PMID 34493285, 2021).
tumor (continued). "Lactic acid, the end product of glycolysis, is produced by tumor cells and is shown to drive M2 polarization of TAMs via activation of the hypoxia inducible factor 1 subunit alpha (HIF-1α) signaling." (PMID 34359674, 2021). "After tumor recurrence, the expression of HIF1A significantly increased, and the correlation between HIF1A expression levels and exhausted T cells and induced regulatory T cells became stronger." (PMID 34305618, 2021). "Taken together, our results confirm the central role of HIF-1α in the interactions between the tumor microenvironment and CLL cells, also elucidating the interplay with the CXCL12/CXCR4 axis." (PMID 34207596, 2021). "Here we elucidated that HIF1α potentially regulates the immune condition of a tumor, especially the IL-17 pathway." (PMID 34595177, 2021). "On the whole, the studies on hypoxia in the TME indicate HIF molecules, in particular HIF-1α, as key players for both the tumor progression and the escape from the NK cell attack (and more widely, from the immune mediated control of the tumor)." (PMID 34696251, 2021). "Our finding that bone metastasis was significantly lower with Hif1α or Hif2α deletion are highly consistent with previous studies demonstrating that hypoxic signaling promotes tumor cell dissemination to the bone." (PMID 34556788, 2021). "HIF-1α also initiates both the glycolytic energy metabolism and angiogenesis and contributes to poor tumor prognosis." (PMID 34771718, 2021). "HIF1α is a hypoxia-inducible factor that plays a key role in tumor cell proliferation and angiogenesis." (PMID 34834367, 2021). "HIF-1α plays a critical role in promoting tumor angiogenesis by activating the transcription of major proangiogenic factors, including VEGF." (PMID 33804393, 2021). "We found that HIF-1α expression was activated during U251 tumour progression between d7 and d21 and was decreased in the BATF2 group at all three different stages." (PMID 33452462, 2021). "HIF-1α is a major subtype identified in the tumor microenvironment and has been found to be a key regulator of tumor growth." (PMID 35280249, 2021). "Among these possible targets, HIF1A was selected for further investigations given its central roles in the hypoxic tumor microenvironment." (PMID 34621671, 2021). "Compared with the control group, the ASP and HIF-1α RNAi groups showed inhibited tumor growth and reduced tumor weight." (PMID 34335854, 2021). "In conclusion, the results showed that, after PDT treatment, POP-Gel downregulates the expression of HIF-1α and VEGF once there is sufficient production of dioxygen, consequently causing the inhibition of tumour growth and metastasis." (PMID 34946732, 2021). "Blood supply to all cancer cells is restricted with tumor progression, and the tumor microenvironment stabilizes HIF-1α and HIF-2α, which are therefore found to be upregulated in tumors; however, this does not apply to all cancer cell types." (PMID 34201062, 2021). "The expressions of HIF‐1α (an indicator of tumor hypoxia), collagen, fibronectin, and elastin (three main components in ECM) were analyzed further to confirm HBO's influence on ECM." (PMID 34085419, 2021). "Tumour spheroid is superior to 2D cell culture as it mimics the tumour microenvironment and the ability to capture HIF-1α due to hypoxia; hence, such a model is widely used in cancer research and drug development." (PMID 34451884, 2021). "Lactate contributes to one mechanism of radioresistance in pancreatic cancer by enhancing the tumor-promoting activity of MDSCs via the GPR81/mTOR/HIF1α/STAT3 pathway." (PMID 33923299, 2021). "HIF-1α is a vital transcriptional mediator that plays an important role in the alteration of tumor cells in response to hypoxia by regulating multiple cytokines that enhance the proliferation and angiogenesis of LC." (PMID 33990544, 2021).